IL15 (interleukin 15)
Diseases named in the same sentence as IL15 in open-access papers (continued):
Sharing a sentence is not in itself a finding about the gene and the disease.
tumor (continued). "Further analysis of IL-15-induced CIK cells demonstrated that the NKG2D receptor is also involved in the recognition of target cells and the main effector cells were CD3+CD8+CD25+CD56− cells, which were more effective compared to conventional CD3+CD56+ cells in the lysis of tumor cells." (PMID 24748966, 2014). "If IL-1α expression in tumor cells is elevated in the absence of IL-15-dependent cell-mediated immunity, and it contributes to tumor cell death in the context of a competent immune system, we asked if IL-1α could be used as a therapeutic target." (PMID 24416335, 2014). "The level of Tax expression per tumor cell was increased in the absence of IL-15." (PMID 24416335, 2014). "However, the mechanisms of CIK cell proliferation and acquisition of cytolytic function against tumor induced by IL-2 and IL-15 have not been well elucidated yet." (PMID 25108500, 2014). "Similarly, the same targeting peptide that enhances IL12 therapies in one model fails to improve the effect of either IL15 or PF4 for inhibiting tumor growth in the same model." (PMID 24369443, 2013). "In this context, it can be speculated that combined stimulation through IL-2, IL-15 and 4-1BB receptors may enhance Ag-specific CD8+ CTL responses induced by E7 DNA vaccines, thereby conferring more effective tumor control in an HPV E7-expressing tumor model." (PMID 24391824, 2013). "We next sought to determine whether IL-15 DCs display any non-specific cytotoxic activity against tumor antigen-specific T cells, which would be unwanted in the context of immunotherapy." (PMID 23284789, 2012). "However, it is important to be aware of the potential side effects of IL-15 on renal epithelial cells, especially tumor cells since until now the IL-15 action in renal physio-pathology is still not completely understood." (PMID 22363690, 2012). "In order to assess whether signaling responses also were altered in tumor-infiltrating T cells in SLL/CLL and MZL, tumor samples were stimulated with IL-2, IL-7 and IL-15 for 15 minutes and phospho-protein levels were evaluated in the CD5+ CD20- T cell fraction." (PMID 23072591, 2012). "A major advantage of IL-15 and IL-21 is that they can maintain the expression of the T cell co-stimulatory molecule CD28 and lymphoid homing markers such as CD62L, which was found to improved the in vivo survival and anti-tumor activity of adoptively transferred T cells in murine model experiments." (PMID 17406677, 2007). "We speculate that a longer observation period would have been necessary, as only around day 19 critical amounts of IL-15-responsive effector cells necessary for anti-tumor responses were reached, but this was not possible due to ethical reasons and limitation by onset of Graft-versus-host-disease." (PMID 38338686, 2024). "The efficacy of tumor eradication in mice by VEGFR2-targeting CAR T cells could be improved by co-expression of secreted IL-12 or IL-15 in CAR T cells, while no overt toxicities against normal tissues were reported that would generally preclude the use of VEGFR2 as a target for CAR T cells." (PMID 39766150, 2024). "The construct design was based on the rationale, that by simultaneous binding to TA-MUC1, higher IL-15 doses could be applied to accumulate in the tumor, without leading to lymphocyte exhaustion and reduced responsiveness after multiple treatments as described for IL-15 superagonists." (PMID 38338686, 2024). "Furthermore, multimodal imaging showed iNSC delivery of RANTES/IL‐15 in combination with intravenous administration of CAR‐T cells reduced established orthotopic GBM xenografts 2538‐fold within the first week, followed by durable tumor remission through 60 days post‐treatment." (PMID 38023712, 2023). "However, the full potential might not be achieved as on-target yet off-tumor effects may occur due to the high affinity of IL-15 to its receptor and as tumor cells might internalize those fusion proteins and limit their targeting to T cells." (PMID 37923822, 2023).
tumor (continued). "Indeed, tumor control stopped only 1 week after the end of the NK cell injections, which may suggest that KLRC1KO NK cells have a very short life span in vivo, despite the presence of human IL-15 in the transgenic mice used." (PMID 37675109, 2023). "In contrast, IL15 expression in the healthy tissues tested (heart, lung, liver, spleen, kidney and brain) was insignificant and similar to that of the non‐targeted (control) particles that did not induce any IL15 mRNA expression in both the tumours and other vital organs." (PMID 35758207, 2022). "Notably, in TCONV, IL-15 promotes a more memory-like metabolic profile, and CD62L is also a central memory marker that is correlated with stem-like properties and enhanced anti-tumor efficacy; together, this further supports the link between iNKT cell metabolism and persistence in a tumor context." (PMID 34434191, 2021). "In addition to IL-12 and IL-18, CAR T cells engineered to secrete IL-7, IL-15, and IL-21 (covered in more detail in the next section), although primarily intended to enhance the persistence and activity of the CAR T cells themselves, will also stimulate anti-tumour responses in bystander cells." (PMID 34885108, 2021). "This high level of IL-15 in the tumor resulted in tissue destruction that occurred rapidly, and though antigen-presenting cells may have been present, the low number of T cells in the tumor did not allow for the generation of an adequate memory response." (PMID 33096755, 2020). "Circulating IL-15 levels could not only potentially be used as a biomarker for CAR T cell expansion, but a pre-clinical xenograft mouse model transduced with GD2 CAR T cells overexpressing IL-15 also showed improved expansion, enhanced anti-tumor activity and improved survival." (PMID 32102342, 2020). "However, IL-15 as a monotherapy did not result in a sustained anti-tumor response." (PMID 33096755, 2020). "Notably, for both IL-13Rα2.IL15-CAR and MUC16ecto.IL-12-CAR T cells, IL-15 or IL-12 production was low at baseline and increased multiple fold in an antigen specific manner, indicating that elevated cytokine levels should be limited to the local tumor environment." (PMID 30828333, 2019). "Lastly, many T cell stimulatory cytokines including IL-2, IL-7, and IL-15 play an important role in enhancing anti-tumor immunity, but whether or not these cytokines render T cells resistant to the suppressive effects of Treg cells in the context of anti-tumor immunity is unclear." (PMID 31058083, 2019). "But we could not observe enhanced or reduced tumor growth in mice when human IL-15 was used." (PMID 29255466, 2017). "Compared with NK cells not exposed to IL-15, IL-15-treated NK cells maintained higher levels of activity with reduced levels of apoptosis, and a higher level of proliferation and cytotoxic activity when cultured with tumor cells or exposed to tumor supernatant." (PMID 28716068, 2017). "Similarly, 50% (4/8) of the treated SK-BR-3 HTM had no, or only a very low level of tumor burden left in the peritoneum upon IL-15/trastuzumab treatment, whereas trastuzumab therapy alone was not sufficient to reduce the amount of tumor cells in any of the treated mice." (PMID 27835865, 2017). "Thus, we would conclude that expansion of Vγ2Vδ2 T cells in IL-15 could help persistence in vivo but without zoledronate treatment to render the tumor cells stimulatory to Vγ2Vδ2 T cells, they would have limited ability to control tumor growth." (PMID 28239463, 2017). "In regards to the ex vivo expansion setting, we could not distinguish any superiority in terms of anti-tumor activity in vivo among IL-7, IL-15, IL-18, IL-21 and no cytokine (NC) conditions, perhaps due to CART cell number being sufficient to eliminate tumor in all the groups." (PMID 27409425, 2016).
tumor (continued). "Moreover, studies have shown that, in the highly dynamic tumor-immune system, the expression of PD-L1 in tumor microenvironment can also be induced by CD8-positive T cells, as well as cytokines such as interferon γ, IL-2, IL-7, IL-15, and IL-21 in a positive feedback mechanism." (PMID 27120796, 2016). "Therefore, in the absence of IL-15, there might be less recruitment of leukocytes in tumor lesions thus decreasing vaccine efficacy." (PMID 25997501, 2015). "Interestingly, IL-1α abundance in the skin surrounding the tumor was independent of IL-15." (PMID 24416335, 2014). "Although the receptor γ-chain has been shown to be indispensible for NK and NKT cell development, we have previously shown that IL-15 may mediate its effects in the absence of this receptor subunit resulting in anti-tumor and anti-viral activity, as well as in activating myeloid immune cells." (PMID 22768089, 2012). "However, IL-15 transgene failed to rescue decreased levels of NK cells after tumor challenge." (PMID 18784839, 2008). "Clinical data from OBX-115, a tumor-infiltrating lymphocyte (TIL) product incorporating drug-inducible mbIL-15 (NCT05470283, NCT05086692), show modest NK cell expansion following IL-15 induction but do not report discontinuation of treatment due to toxicity." (PMID 40519930, 2025). "A further issue is the limited expansion of CAR-NK cells in vivo after transplantation, due to tumour heterogeneity and a lack of cytokines, e.g., IL2 and IL15." (PMID 40650066, 2025). "CAR T cells co-expressing soluble or membrane-bound IL-15 provide enhanced tumor cytotoxicity, increased expansion, decreased exhaustion and a higher frequency of TSCM and TCM cells compared with parental CAR T cells lacking IL-15 enhancement." (PMID 40519930, 2025). "Five cytokines—IFN‐γ, TNF‐α, GM‐CSF, IL‐2, and IL‐15—were detected only in the CSF of MUE cases and not in IE or neoplasia cases." (PMID 40859633, 2025). "Finally, the development of CAR-T cells engineered to secrete proinflammatory cytokines (such as IL-12, IL-15 and IL-18), to produce molecules engaging tumor cells by not engineered T cells, as well as the development of strategies to overcome cell exhaustion could also be required." (PMID 40092980, 2025). "For example, induced pluripotent stem cell (iPSC)-derived NK cells expressing high affinity non-cleavable CD16, and membrane-bound IL-15/IL-15R in combination with silenced CD38 expression have demonstrated enhanced persistence and anti-tumour functions." (PMID 38223411, 2024). "Actually, periphery CD16-CD56 + bright/dim NK cells do not start with anti-tumor activity, but can rapidly proliferate and transform into CD16CD56+bright NK cells after stimulation by cytokines (IL-2, IL-12 and IL-15) to acquire anti-tumor cytotoxic capacity." (PMID 38245747, 2024). "Based on target cell expansion (CD8+ or CD4+ effector memory T cells) in tumor and peripheral blood (data not shown), 0.01 mg/kg of PD1/IL15 TaCk was identified as mPAD in a humanized (hCD34+ engrafted in NSG) mouse model." (PMID 38887559, 2024). "In mice models of intraperitoneal ovarian cancer, MCAR15-Vδ2T cells exhibited superior tumor control and prolonged persistence in the tumor and organs at day 57 (as compared to normal CAR Vγ9Vδ2 T cells without IL-15)." (PMID 38665921, 2024). "Remarkably, without IL-15/IL-15Rα, K2-Fc alone had modest impact on most lymphocyte activation markers, besides CD137 on NK cells, and was not able to drive anti-tumor immune responses profoundly." (PMID 37923822, 2023). "Considering the nonspecific distribution of free drug and the tumour and LNs accumulation of NIL-IM-Lip, we focused on comparing the immune cell changes between the IR780 + 1-MT + IL-15 + L group and the NIL-IM-Lip+L group." (PMID 37076492, 2023). "IL-15 alone had no influence on the growth of mouse TSA breast tumors (poor immunogenicity), but significantly enhanced tumor response when combined with RT." (PMID 37833255, 2023).
tumor (continued). "For example, IL-15 co-expression in CAR-NKT cells increases their localization at the tumor site and improves tumor control without any toxic effects." (PMID 37158883, 2023). "Notably, compared with the IR780 + 1-MT + IL-15 + L group, the NIL-IM-Lip+L group exhibited better immune cell regulation in the TLIME, verifying that the pH/MMP2/temperature triple-sensitive immunomodulatory nanoinducer NIL-IM-Lip could accumulate in tumour tissues and be directed to the LNs." (PMID 37076492, 2023). "Although IL-15 expanded the numbers of NK1.1+ cells, anti-asialo-GM1 (injected to deplete these cells) did not influence the tumor growth, while CD8 depletion abrogated the antitumor effects of IL-15 and triple combination treatments." (PMID 34830209, 2021). "Quantification of spheroid size and fluorescent intensity further highlights the differences in tumor killing mediated by NK cells treated with the CAM1615HER2 TriKE versus cells treated with the no treatment, CAM16, or IL15 controls." (PMID 34439149, 2021). "In a pre-clinical setup, this design improved in vivo persistence and tumor infiltration, as well as limiting to a greater extent the tumor growth, compared to GD2 CAR NKT cells that do not express IL15." (PMID 35008348, 2021). "The results showed that a single infusion of CAR.19/IL15+ CB-NK cells can control tumor progression and increase survival through improving their cancer recognition and cytotoxic activity in comparison to CAR.19/IL15-negative NK cells." (PMID 33752707, 2021). "While we did not see any difference of TNF-α, IL-15, and IFN-γ secretion between the tumor and the adjacent healthy tissue, we showed a trend with a higher production of IL-6 in tumor." (PMID 31105699, 2019). "IL15 presents different advantages compared to IL2, including the preferential activation and expansion of memory CD8 and NK cells that promote tumor control with no-Treg expansion." (PMID 31614774, 2019). "Plasma levels of the NK cell-activating cytokines IL-2, IL-15, IL-18, and IL-21 increased substantially within the first 2 days after CY+TBI compared to their plasma levels in 4T1 tumor-bearing mice not subjected to chemo-irradiation." (PMID 27915436, 2017). "In fact, recent published work using CAR constructs incorporating IL15 show prolonged persistence of NK CAR cells, without negative effects on overall cytotoxicity and observations of anti-tumor activity." (PMID 29348865, 2017). "Tumors in mice receiving IL-7, IL-15, IL-18, IL-21, and NC exposed CART cells regressed or even disappeared, without any statistical difference in tumor size at the end point." (PMID 27409425, 2016). "While IL-15 KO/MT tumor CD8 T cells had high levels of exhaustion markers (PD-1) and lacked IFNγ production, IL-15 TG/MT CD8 T cells had very low levels of PD-1 and produced large amounts of IFNγ." (PMID 25879689, 2015). "We observed increased CD8 T cells within IL-15 TG/MT tumors, but CD8 T cells within the tumor are not always functional as they can be anergic and/or exhausted." (PMID 25879689, 2015). "Long-term antibody depletion studies in IL-15 TG/MT mice revealed that NK1.1+, but not CD8 T cells, were critical for tumor destruction." (PMID 25879689, 2015). "Although multiple granzyme genes in CD8+ TIL were increased with IL-15 complexes and anti-PD-1 treatment and correlated with the overall influx of CD8+ T cells within the tumor parenchyma, the gene expression of granzyme B was not increased as determined using Nanostring®." (PMID 41373645, 2025). "Finally, ex vivo culture of CAR T cells in IL-7 and IL-15 rather than traditional IL-2 is also known to favour the central memory (TCM) phenotype and increase tumour control." (PMID 37291434, 2023). "In addition, unlike the case for IL-15/PD-1 blockade, mice treated with OMCPmutIL-2 in combination with anti–CTLA-4 remained resistant to tumor rechallenge without additional treatment, suggesting long-term immunity." (PMID 35603788, 2022).
tumor (continued). "Moreover, GPC-3-CAR/sIL-15 Vδ1 T cells displayed greater proliferation and stronger anti-tumor responses when compared with GPC-3-CAR Vδ1 T cells lacking sIL-15, suggesting IL-15 signal was critical for CAR Vδ1 T cell function." (PMID 35747139, 2022). "Recently, a clinical trial showed that IL-15 can increase CD8+ T cell and NK cell numbers up to 5.8 and 38 times that of the control group, respectively, and 17 of the 27 patients treated with IL-15 showed no tumor progression." (PMID 36582246, 2022). "From visualizing our FACs data, we observed that the decrease in live tumor cells in the presence of the ADU-S100 and IL-15 combination was not due to a lack of proliferation of the tumor cells as we observed a clear reduction of live CD45 negative cells and an increase in dead cells." (PMID 33777767, 2021). "Similarly, when we incubated the same siMSI2s with primary CLL cells co-cultured with or without HS5 feeder cells with or without CpG-ODN + IL15, each condition resulted in a significant MSI2 decrease in tumor-cell survival compared to the control." (PMID 33504942, 2021). "Infusing Perforin-/- CD137L/IL-15/IL-15Rα activated NK cells had no impact on GVT, whereas TNF-α-/- CD137L/IL-15/IL-15Rα activated NK cells improved GVT by decreasing peripheral effector cell subsets while preserving tumor-infiltrating lymphocytes." (PMID 34489927, 2021). "Tumor cell death was evaluated in co-cultures containing non-adherent PBMCs and either LNCaP or PC3 cancer cells incubated for 48 h in the presence of the cytokine IL-15, the ADU-S100 analog, or a combination of both." (PMID 33777767, 2021). "Immune cells stimulated with IL-15 produce high levels of IFN-γ and TNFα, and IL-15’s strong immune-stimulatory activity coupled with an apparent lack of toxicity made it a promising candidate for tumor therapy." (PMID 33133514, 2020). "This drastic change of NK cell number was not attributable to changes of CXCR4 and CXCR3 ligand expression levels since CXCL10 expression in the BM was not modulated by NK cell transfer or IL-15 administration, nor was the expression of CXCL10 and CXCL12 by BM tumor cells." (PMID 31699153, 2019). "Here, we cultured MNCs from ascites of OC patients or PB of healthy controls overnight in the presence of IL-15, whereupon total cells were challenged for 4 hours with either K562 (control), SKOV-3 OC or without tumor cells and subsequently analyzed by flow cytometry." (PMID 30410679, 2018). "It is also possible that IL-15 overexpression may induce non-specific proliferation of CD8 T cells, not tumor specific responses." (PMID 25879689, 2015). "CARζ/CPR41BB cells (n = 6 donors) expanded comparably in media containing IL-7 and IL-15 (P = not significant; two-way ANOVA with the Tukey test) and exhibited proliferative capacity similar to that of second-generation CART (n = 3 donors) when exposed to HER2+/PD-L1+ tumor cells for 72 hours." (PMID 39973814, 2025). "IL-15 appears less harmful to the TME than IL-2, as it fails to activate Tregs in a similar manner to IL-2, and occasionally inhibits Tregs.IL-15 may be more efficient than IL-2 in tumor suppression." (PMID 40469178, 2025). "To test whether this enhanced IL-15 signaling led to enhanced function, we incubated pbNK cells or eNK cells with the SS1 TriKE or an equifunctional dose of IL-15 for 7 days in severe hypoxia, in the absence of any tumor target." (PMID 39475618, 2024). "The approach of fusing IL-15 to mAbs or their fragments has been increasingly pursued in the last years, however, the targets of these next-generation immunocytokines (e.g., PD-1, PD-L1, LAG3, CD20) are not tumor-specific, but rather broadly expressed on healthy cells." (PMID 38338686, 2024). "However, with IL15 knockdown and PES1 knockdown have no reduction in tumor volume and weight." (PMID 36959575, 2023).